CXCL10 (C-X-C motif chemokine ligand 10)
Diseases named in the same sentence as CXCL10 in open-access papers (continued):
Sharing a sentence is not in itself a finding about the gene and the disease.
COVID-19 (continued). "Cytokine profiling of COVID-19 samples mainly with patients admitted in the intensive care unit has shown an increase in IL-2, IL-7, GM-CSF, IFN- γ inducible protein 10 (IP-10; CXCL10), MCP-1, MIP-1, and TNF- α which could cause viral-induced hyper-inflammation." (PMID 34696521, 2021). "Based on current knowledge, it would seem that more than one cytokine, chemokine, or infiltrating cell type is involved; however, at present, the interplay among IL-6, CXCL10, and macrophages, could represent a main circuit for the onset maintenance and progression of CS in COVID-19." (PMID 33981314, 2021). "Likewise, higher levels of CCL2, CCL7, CCL20, and CXCL10 were associated with lower blood lymphocyte count and higher inflammatory markers (CRP and ferritin), which are clinical markers of severe disease and poorer outcome in COVID-19." (PMID 33704068, 2021). "In this in silico study, we analyzed ACE2 and CXCL10 in terms of expression pattern, functional characterization and mutation in lung adenocarcinoma (LUAD) and lung squamous cell carcinoma (LUSC) to assess their possible involvement in the severe prognosis of COVID-19 in patients with lung cancer." (PMID 33585826, 2021). "Also, we found 6 existing drugs against 4 potential anti-COVID-19 targets (CCL20, CSF3, CXCL1, CXCL10) that might have novel anti-COVID-19 indications." (PMID 34582497, 2021). "Also, a clinical trial assessing the use of serial CXCL10 measurement as a clinical decision support for patients with COVID-19 recently completed enrollment (NCT04389645) supporting the notion that this may be an actionable target in this patient population." (PMID 34582497, 2021). "Additionally, the FDA-approved 3-hydroxy-3-methylglutaryl-CoA (HMG-CoA) reductase inhibitor atorvastatin inhibits CXCL10 and may be useful in the treatment of COVID-19." (PMID 32973504, 2020). "Another popular candidate, Lianhuaqingwen (LH), was shown to significantly inhibit SARS-CoV-2 replication in Vero E6 cells and markedly reduce production of pro-inflammatory cytokines (TNF-α, IL-6, CCL-2/MCP-1 and CXCL-10/IP-10), suggesting that it might be a potential option for COVID-19 treatment." (PMID 33643033, 2020). "Taken together, we demonstrate that CXCL10 is an important cytokine secreted from infected airway epithelial cells, and that these cells are unlikely to be the source of classic pro-inflammatory cytokines such as IL-6 and TNFα reported to be elevated in the systemic circulation of COVID-19 patients." (PMID 33284849, 2020). "A report demonstrated that CXCL10 (IP-10) inhibits endothelial recovery independently of any other inflammatory factor, and anti-CXCL10 antibody is under validation in a clinical trial to prevent cardiovascular events because the more severe the COVID-19 patient, the higher the serum IP-10 level." (PMID 33121429, 2020). "Because cytokine and chemokine levels are relevant in the context of ARDS patients with COVID-19, serum levels of CXCL9 and CXCL10 during the acute phase were compared to both chemokines’ levels during recovery phases (4 months post-infection)." (PMID 41425601, 2025). "Four months after COVID-19, patients with prior ARDS and persistent pulmonary sequelae exhibit sustained elevations of anti-SARS-CoV-2 IgG and chemokines CXCL9 and CXCL10." (PMID 41425601, 2025). "In the context of COVID-19, chemokines such as CCL2 (MCP-1) and CXCL10 (IP-10) have been identified as key players in mediating immune cell migration and activation, which are crucial in the development and persistence of inflammation." (PMID 40094929, 2025). "The aim of this work was to evaluate the associations of polymorphisms in the TNF-α, IL-6, IL-8, IL-10, CCL5 and CXCL6 genes with COVID-19 outcomes and with the serum levels of IFN-α, IFN-γ, TNF-α, IL-1Ra, IL-6, IL-7, IL-10, CCL2, CCL3, CXCL8, CXCL10 and GCSF." (PMID 40881695, 2025).
COVID-19 (continued). "Neutrophils from severe COVID-19 cases exhibit a hyperinflammatory profile, with upregulated expression of IL1β, CXCL10, and S100A8, corroborating the findings of cytokine storm syndromes reported in severe COVID-19." (PMID 39928675, 2025). "A key finding of this study is the significant correlation between serum levels of the chemokines CXCL9 and CXCL10 and anti-SARS-CoV-2 IgG titers in patients recovering from COVID-19." (PMID 41425601, 2025). "Multiple studies show high levels of proinflammatory cytokines such as IL-1, TNF, IFNs, IL-6, IL-8, IL-18, IL-17α, G-CSF, and GM-CSF, as well as chemokines, such as MCP-1, IP-10, MIP-1α, CXCL10, CCL2, CCL4, CCL14, CCL19, and CCL25 in severe cases of COVID-19." (PMID 40076291, 2025). "In the CoVonly group receiving only the third booster dose of COVID-19 vaccine, we found, on 1 day (d1) post-immunization, a strong increase of the cytokines IL-15, IL-6, TNF-α and IFN-γ as well as of the chemokine CXCL10." (PMID 39340080, 2024). "This is the first study reporting the significance of GM-CSF, CXCL10 and CD27−CD28− CD8+ T cells in the severity of COVID-19 specifically in an older population." (PMID 38715114, 2024). "Maternal samples were positive in PC2, defined by significant contribution from IP10 (CXCL10) and IL4, factors that have been previously identified as serum biomarkers of COVID-19 severity." (PMID 39845965, 2024). "In one study, it was noted that the activation of the innate immune system and cytokine storms (featuring elevated levels of TNF, IL-6, CXCL10, CCL2, CCL5, and IFN2) play crucial roles in the pathogenesis of COVID-19." (PMID 39685844, 2024). "A comparative analysis of patients diagnosed with COVID-19, COVID-19 with concurrent maculopapular rash, or DRESS found that there were similar elevations of CXCL9, CXCL10, CXCL11, IFN-γ, IL-10, TNF-α, and IL-18 across the three groups." (PMID 39318634, 2024). "These molecules modulate CS in COVID-19, notably meloxicam, which exhibited a downregulatory effect on cytokines (IL-6, CCL2, GM-CSF, CXCL10, IL-2, and TNF-α)." (PMID 39518964, 2024). "Cytokine profiling of the sera of patients with COVID-19 and the transcriptional analysis of their BAL fluid revealed increased IL-6, G-CSF, CXCL10, CCL2, CCL3, and TNF-α levels, correlating with disease severity and progression." (PMID 39417078, 2024). "Several biomarkers, such as TNF-related apoptosis-inducing ligand (TRAIL), interferon gamma-induced protein 10 (IP-10 or CXCL10), and C-related protein (CRP), have been identified as indicators for assessing the severity of COVID-19." (PMID 38572318, 2024). "Regarding chemokines, the spike-specific IgG/IgM were associated positively with C-X-C motif ligand (CXCL) 5 but negatively with C-C motif ligand (CCL) 4, CXCL9, CXCL10, and CXCL11, which were reportedly upregulated in severe COVID-19." (PMID 38377029, 2024). "Despite these differences, prior research has consistently shown elevated inflammatory cytokines, such as IFN-γ, IL-10, IL-6, IL-8, CXCL10, MIP-1α, MIP-1β, TNF-α, and IL-17 in MIS-C patients compared to healthy controls and other pediatric COVID-19 cases." (PMID 39931580, 2024). "In patients with severe COVID-19, anti-SARS-CoV-2 antibodies and pro-inflammatory cytokines and chemokines (IL-6, CXCL-10, and HGF) were significantly elevated." (PMID 39063142, 2024). "In support of this model, samples collected within 48 hours of intubation from patients with COVID-19 clustered distinctly from other patient groups, driven by CXCL10 and CCL8 in BAL samples and CXCL10 in plasma." (PMID 38502186, 2024). "The main inflammatory cytokines and chemokines widely produced by patients with severe forms of COVID-19 are IL-6, IL-8, IL-1β, TNF-alpha, IFN-gamma, MIP1α and 1β, CCL2, CCL5, CCL20, CXCL1, CXCL2, CXCL8, CXCL10, and CXCL17." (PMID 39768136, 2024).
COVID-19 (continued). "There is a notable decrease in anti-inflammatory microorganisms, such as Faecalibacterium prausnitzii and Eubacterium rectale, in COVID-19 patients, which corresponds with elevated levels of tumor necrosis factor (TNF), interleukin-10 (IL-10), and CXCL10." (PMID 38779486, 2024). "In patients with severe COVID-19, a high correlation was observed between circulating inflammatory cytokines, such as IL-6, CXCL10 (IP-10), and CSF1 (M-CSF), and arginine metabolism as well as tryptophan metabolism." (PMID 39759510, 2024). "Higher neutralizing activity in participants with the OP pattern, rather than a stronger innate immune response (IFN-α and CXCL10), is considered to be consistent with the better prognosis of OP because an earlier humoral immune response has previously been linked to a better prognosis of COVID-19." (PMID 37376606, 2023). "For instance, analysis of transcriptomic data in bronchoalveolar lavage of a patient with COVID-19 found high expression of CCL2, CCL3, CCL4, and CXCL10 when compared to healthy donors." (PMID 37632046, 2023). "The transcription factor NF-κB is activated during viral infections, including COVID-19, and while upregulated it stimulates the production of chemokines such as monocyte CCL2 and CXCL10, which were also significantly upregulated in our study." (PMID 37832397, 2023). "It was reported that COVID-19 patients exhibited high plasma levels of C-C motif chemokine ligand 2 (CCL2), CXCL10, IFN-γ, IL-1β, IL-7, IL-8, IL-10 and TNF-α." (PMID 37251383, 2023). "CXCL9, CXCL10, CXCL11, and CXCR3 levels were significantly higher in patients with severe COVID-19 group than in those with moderate disease." (PMID 37493737, 2023). "Patients infected with COVID-19 have high levels of IL-1β, IFN-γ, IP-10/CXCL10, and MCP-1/CCL2, leading to activated T-helper-1 (Th1) cell responses." (PMID 36851766, 2023). "The levels of CXCL9, CXCL10, CXCL11, and CXCR3 were significantly higher in patients with COVID-19 than in healthy controls." (PMID 37493737, 2023). "Three cytokines/chemokines, IL-6, CXCL-10, and HGF, were found to be highly elevated in plasma samples of severe COVID-19 patients compared to mild/moderate patients." (PMID 37685858, 2023). "Clinical evidence suggests that patients with severe COVID-19 have markedly increased levels of pro-inflammatory cytokines within their bodies, including IL-1β, IL-2, IL-6, IL-7, IL8, TNF-α, CCL2, MIP-1α, and CXCL10." (PMID 37163438, 2023). "Elevated CXCL10 levels are correlated with COVID-19-related ARDS and neurological complications and is considered a predictive biomarker of COVID-19 severity and disease progression." (PMID 37998327, 2023). "Gut microbiota composition of COVID-19 patients was found to be connected with plasma concentrations of aspartate aminotransferase (AST), C-X-C motif ligand 10 (CXCL10), CRP and lactate dehydrogenase (LDH)." (PMID 37205106, 2023). "This study examined the relationship between levels of the chemokines CXCL9, CXCL10, CXCL11, and CXCR3 and mortality in patients with COVID-19.." (PMID 37493737, 2023). "In genomic studies, some up-regulated homologous chemokines such as CXCL9, CXCL10 and CCL5, which are involved in the regulation of immune cell migration and activation in IPF, were also detected in COVID-19 patients." (PMID 37391786, 2023). "Gene expression differences between COVID-19 patients and healthy controls revealed that CCR2, CXCL10, I-κB, NF-κB and Nrf2 were significantly upregulated when analyzing the log2fold change expression values, the iNOS gene showed tendencies." (PMID 37832397, 2023). "CXCL10 is critical for CD8+ and CD4+ T cell recruitment and has been demonstrated to correlate with the severity of COVID-19." (PMID 37112926, 2023). "Microbe-mediated amino acids were positively associated with increased levels of inflammatory cytokines (CXCL9, CXCL10, IFN-γ and IL-6) and negatively correlated with decreased levels of cytokines (IL-9 and IL-17) in COVID-19." (PMID 37205106, 2023).
COVID-19 (continued). "They noted high levels of Interleukin (IL)-1β, IL-6, Interferon (IFN)-γ, C-X-C motif chemokine ligand 10 (CXCL10), and C–C motif chemokine ligand 2 (CCL2) in COVID-19 patients as signs of T-helper-1 cell activation." (PMID 37003990, 2023). "COVID-19 patients showed significant correlations (all p < 0.01) of hs-CRP with IL8 (r = 0.421), MCP3 (r = 0.660), CXCL10 (r = 0.391), CCL23 (r = 0.555), and IL6 (r = 0.687)." (PMID 37832397, 2023). "Inspection of a previously published spatial data set of alveolar tissue (which did not discriminate between mild and severe DAD) confirmed upregulation of STAT1, CXCL10, BAFF, and TRAIL in COVID-19." (PMID 36472908, 2023). "Previous work has shown that IL1B, IL18, and CXCL10 are induced by SARS-CoV-2 infection and contribute to COVID-19 pathogenesis." (PMID 37737611, 2023). "In the ROC curve analysis of the ability of CXCL9, CXCL10, CXCL11, and CXCR3 to discriminate between moderate and severe COVID-19, the AUC values were 0.702, 0.939, 0.933, and 0.857, respectively." (PMID 37493737, 2023). "Cytokine IFNA7, as well as chemokines CXCL13, CXCL10, CCL7, and CCL8 were present in the proteins selected for predicting severe COVID-19." (PMID 37069249, 2023). "In severe cases of COVID-19, multiple studies have indicated higher levels of IL-2, IL-6, IL-7, IL-10, CXCL10(IP-10), CCL2 (MCP-1), TNF-α, CCL3(MIP-1α), and G-CSF when compared to patients with mild and moderate infections." (PMID 37834246, 2023). "CXCL10/IP-10 was significantly elevated at all times of infection, and GDF-15/MIC-1 had considerably higher levels in all patients with COVID-19." (PMID 36851766, 2023). "PRAD is a prevalent cancer type in males, and multiple biomolecules that act as markers of PRAD are in common with COVID-19 (Both TMPRSS2 and CXCL10 were upregulated in PRAD patients)." (PMID 36239108, 2022). "Following the analysis of the large data collection, 20 curated genes were identified as biomarkers or therapeutic candidates for COVID-19 therapy, including TMPRSS2 and CXCL10." (PMID 36239108, 2022). "Furthermore, the levels of CXCL10, a key chemokine produced by activated bronchial and alveolar epithelial cells in response to infections and involved in the etiology of various pulmonary conditions (such as pulmonary fibrosis), have been found to be increased early in COVID-19 patients." (PMID 35844604, 2022). "The results of RNA-sequencing analysis show that several inflammatory factors, including IL-6, TNF, CXCL8, CXCL2, CXCL3, CXCL10, CXCL11, and NF-κB were upregulated, which is consistent with the clinically observed phenomenon in COVID-19 patients." (PMID 36578545, 2022). "Seven out of the 16 known cytokine markers (including IL1A, IL1R1, CCL2, IL6, IL10, CXCL10, and VEGFA) were less pronounced in KD than in severe COVID-19 patients compared to FC and HC, respectively." (PMID 36159873, 2022). "Collectively, all the cytokines and chemokines contribute to COVID-19 immunopathology, yet IL-6, IFN, IL-17, TGF-β, TNF-α, and CXCL10 are believed to have major roles in the lung pathogenesis post-SARS-CoV-2 infection." (PMID 35062368, 2022). "A positive correlation was found between COVID-19 BAL fluid levels of IL-15 and CXCL10 or CCL2, cytokines/chemokines involved in monocyte, lymphocyte, and NK cell functions." (PMID 34793331, 2022). "The results show that TGF-β, CXCL-10, IFN gamma, and IL-7 affect mortality in COVID-19 patients in a univariate regression analysis." (PMID 36286038, 2022). "MMP-7, TGF-β, CCL2, CCL-3, CXCL-10, G-CSF, IFN gamma, IL-10, IL-2, IL-4, IL-6, IL-7, TNF-α, IL-6, and IGF-1 were studied for their correlation to lung involvement in COVID-19 patients." (PMID 36286038, 2022). "As an indication of disease severity, we measured the mRNA expression levels of IFN-stimulated genes (IFIT1, IFIT3, ISG15, and MX2), pro-inflammatory cytokines (IL6, IL10), and chemokines (CXCL10, CCL2) that are correlated with COVID-19 exacerbation." (PMID 35562337, 2022).
COVID-19 (continued). "Hence, CXCL10 might be a suitable target to reduce lung inflammation in COVID-19 patients." (PMID 35674675, 2022). "The findings showed that compared to healthy controls, patients with COVID-19 had significantly higher levels of interleukins 1α, 2, 6, 7, 8, 10 and 15, CRP, SAA, ICAM-1, VCAM-1, CXCL10, CCL3, CCL26, IFN-γ, TNF-α, bFGF, PlGF, and Flt-1." (PMID 35958594, 2022). "Of the 16 mediators elevated in early COVID-19 compared with healthy controls, 11 decreased over time (CCL3, CCL4, TNF-α, IL-6, CCL13, IL-4, IFN-α2a, CXCL10, CXCL11, IL-2, and IL-12)." (PMID 35397798, 2022). "The inhibition of the CXCL10/CXCR3 pathway reduces inflammation and cytokine storm in response to COVID-19." (PMID 35409036, 2022). "Many investigations have reported high levels of pro-inflammatory cytokines and chemokines, including IL-2, IL-6, IL-10, IFN-γ, CXCL10, and CCL2 in COVID-19." (PMID 35664675, 2022). "In this study, we identified 1,656 genes co-expressed with CXCL10 in both PRAD and COVID-19 and 2,669 genes co-expressed with TMPRSS2 for the same." (PMID 36239108, 2022). "COVID-19 patients have been shown to have higher levels of chemokines such as CCL3, CCL5, CXCL10, CCL19, CCL20, while CCL5 remained unchanged." (PMID 35782361, 2022). "MMP-7, TGF-β, CCL2, CCL-3, CXCL-10, G-CSF, IFN gamma, IL-10, IL-2, IL-4, IL-6, IL-7, TNF-α, IL-6, and IGF-1 were studied for their correlation with mortality in all 40 COVID-19 patients." (PMID 36286038, 2022). "We observed increased levels of chemokines MCP-1 (CCL2), IP-10 (CXCL10), MIP1β (CCL4) and IL-8 (CXCL8) in COVID-19 patients." (PMID 35529862, 2022). "In post-COVID-19 patients, some plasma cytokines (i.e. TNF-α, IL-18, CXCL8, CXCL10, CCL2, CCL3, and CCL4) remained higher than in HCs, but levels were much lower as compared to hospitalised patients." (PMID 36275702, 2022). "CXCL10, IL-17, and TNF-α, among the cytokines increased by COVID-19, have established roles in osteoblast proliferation and osteoclastogenesis, resulting in a reduced bone mineral density." (PMID 35159388, 2022). "Remarkably, severe influenza and COVID-19 also converge in elevated levels of chemotactic (CXCL8, CCL2, CCL3, and CXCL10) and activating molecules (G-CSF) acting on monocytes and neutrophils." (PMID 35674675, 2022). "TNF-, IL-2, IL-6, IL1B, IL7, IL10, IFN-, GCSF, CXCL10, CCL2, ferritin, D-dimer, fibrinogen, leukocytosis, and C-reactive protein (CRP) levels are significantly higher in critically ill COVID-19 patients." (PMID 35645351, 2022). "Nevertheless, we found markedly lower levels of IFNG-induced chemokine CXCL10 in KD and CXCL9 and IL15 in both KD and severe COVID-19, suggesting blunted type II interferon signaling in both KD and severe COVID-19 conditions." (PMID 36159873, 2022). "Based on these facts, it can be suggested that coexpressed genes of TMPRSS2 and CXCL10 in both PRAD and COVID-19 play an active role in mediating the pathways responsible for disease prognosis." (PMID 36239108, 2022). "The disease is also associated with the elevated blood levels of other chemokines such as CCL2/MCP-1, CCL3/MIP-1α, CCL4/MIP-1β, CXCL9/MIG, CXCL10/IP-10 and CX3CL1/Fractalkine, which shows that CXCL1 is only one of many COVID-19 factors." (PMID 36613652, 2022). "Overall, 1,656 and 2,669 genes co-expressed with CXCL10 and TMPRSS2 respectively, were found to be common prostate cancer and COVID-19 progression." (PMID 36239108, 2022). "Repeating the analysis to only include first samples, showed again increased levels of CXCL9 and CCL20 in severe disease, but also increased levels of CXCL10 and a downregulation of CCL17 in patients with severe COVID-19." (PMID 34957382, 2022). "Regarding the chemokines, COVID-19 patients showed gene expression levels of CXCL8 and CXCL9 similar to control subjects, but increased expression levels of CXCL10 and CXCL11 (by 290% and 150%, respectively)." (PMID 36009555, 2022).